EGFR (epidermal growth factor receptor)
Diseases named in the same sentence as EGFR in open-access papers (continued):
Sharing a sentence is not in itself a finding about the gene and the disease.
tumor (continued). "Specifically, they discovered an unexpected phenomenon in which EGFR inhibitors decreased the number of tumor cells with high levels of EGFRvIII in vitro and in vivo, and after drug removal, the tumor cells containing a high copy number of EGFRvIII returned, which exceeded the classical genetics." (PMID 33046109, 2020). "In addition, tumor cell-derived EVs transfer membrane-bound epidermal growth factor receptor (EGFR) to endothelial cells." (PMID 32499786, 2020). "The EGFR plays an important role in tissue homeostasis and tumor progression." (PMID 32252690, 2020). "Mice with EGFR-19 del LLC cell tumours had lower numbers of CD8+ and CD4+ cells." (PMID 33143170, 2020). "EGFR overexpression, found both in primary tumour and CTCs, was an indicator of poor prognosis." (PMID 32901137, 2020). "Given the importance of EGFR overexpression for tumor survival, growth and drug resistance, future studies are needed to explore whether overexpressed EGFR knockout can be an option for more cancers." (PMID 32413049, 2020). "The most common interaction with the receptor on the tumor cells was composed by the pair EGFR and HBEGF, which could tend to promote tumor growth." (PMID 33155039, 2020). "Numerous studies have reported that EGFR activation promotes multiple tumor progression." (PMID 33643898, 2020). "EGFR signaling regulates tumor growth through its downstream AKT and ERK pathways." (PMID 32883032, 2020). "In addition, significant detectable levels of Urokinase Plasminogen Activator Receptor (UPAR) and Epidermal Growth Factor Receptor (EGFR) were found in tumor biopsies of who patients who relapsed after vemurafenib treatment." (PMID 33419275, 2020). "The goal was to prolong survival time with gene therapy aimed at knocking down the tumor EGFR mRNA." (PMID 35047884, 2020). "Interaction between PGRMC1 and EGFR has been shown to promote tumor growth." (PMID 32867363, 2020). "While these known mechanisms of EGFR therapy resistance account for approximately 70% of patient relapses/failures, these molecular events do not explain the mechanisms of resistance in approximately 30% of patients with tumor recurrence." (PMID 33112928, 2020). "Rechallenge of anti-EGFR therapy could be defined as retreatment after a progression while on treatment, for a tumor that initially displayed sensitivity to the therapy." (PMID 32825275, 2020). "Furthermore, we evaluated two approaches to detect the presence of MET on circulating tumor cells (CTCs), using the CellSearch® and Parsortix systems and monitored patients under anti-EGFR treatment (n = 30) combining both cfDNA and CTCs analyses." (PMID 32102486, 2020). "Immunohistochemistry for EGFR was performed on all tumour tissue samples." (PMID 32058674, 2020). "Among these selected radiomics features, GLSZM_HGLZE from CT images measures the distribution of the higher gray-level values with a higher value indicating larger high-density areas proportion in tumor, which suggested that the tumors with EGFR+ had lower density than the EGFR- group in our study." (PMID 33134170, 2020). "For example, HSP90 can stabilize HER2, AKT, Raf-1, EGFR (epidermal growth factor receptor), and many other proteins involved in cell proliferation pathways, which could help to drive tumor progression." (PMID 31752169, 2019). "EGFR overactivation may result in the resistance of tumor cells to chemotherapy and radiation treatment, via the activation of the PI3K/Akt, JAK/STAT3 and Ras/Raf/MEK/Erk downstream signaling pathways." (PMID 30947731, 2019). "Considering that tumor cells with EGFR-TKI resistance may manifest stem-cell-like properties, we then analyzed whether PC9/ER cells exhibited a CSC phenotype." (PMID 31801598, 2019). "However, EGFR is a transmembrane protein as well and overexpressed in a wide variety of tumor cells." (PMID 31316001, 2019).
tumor (continued). "Increased proliferation and angiogenesis by EGFR are thought to be caused by the binding ligands TGFα and EGF, which have shown to function as chemoattractants for endothelial cells and promote the expression of VEGF by tumor cells." (PMID 31303863, 2019). "Moreover, increased expression of MOR is associated with progression of NSCLC and the activation of MOR leads to tumor growth by coactivating epidermal growth factor receptor (EGFR) pathways." (PMID 31024840, 2019). "Loss of tumor antigen expression in our models might have an impact in the anti-tumor activity of EGFR expressing T cells." (PMID 31921216, 2019). "In contrast, all tumors strongly express EGFR and the hair follicle stem cell marker SOX9 at the highly proliferative tumor-stroma interface, whereas central tumor regions with a more differentiated stratum spinosum cell type lack both EGFR and SOX9 expression." (PMID 31867038, 2019). "Animals carrying floxed alleles of the EGFR locus did not develop PanIN lesions or PDAC tumors even in the context of pancreatic injury (pancreatitis) or lacking the p16Ink4a/p19Arf tumor suppressors." (PMID 31480737, 2019). "The epidermal growth factor receptor (EGFR) is widely up-regulated in solid tumors and mediates many characteristics of malignant phenotype, including proliferation, tumor cell motility and cell survival marking it as a good target for therapeutic intervention." (PMID 31139331, 2019). "EGFR-T790M mutation was detected in five patients (18.5%) through liquid biopsy, in whom tumor re-biopsy was not conducted." (PMID 30875919, 2019). "Next-generation sequencing (NGS) of the CSF revealed an EGFR G719A mutation (frequency: 55.63%), whereas sequencing of circulating tumor DNA or cells in the peripheral blood identified no clinically significant mutations." (PMID 31396478, 2019). "In addition, this protein also plays a key biological role in the regulation of tumor-related signaling pathways, especially the EGFR pathway." (PMID 31013819, 2019). "Furthermore, immunostaining of tumor sections revealed the presence of residual EGFR-positive cells that directly reflected their viability after cetuximab treatment." (PMID 30213849, 2019). "In this regard, markers of primordial cancer stem-cells, such as Oct4 and CD133, have been detected in NSCLC cell lines and in tumor specimens of EGFRM+ NSCLC patients with acquired resistance to EGFR-TKIs, suggesting that they play a role in the resistance process." (PMID 31266248, 2019). "Therefore, more preclinical experiments are needed to elucidate the mechanism of chemotherapies used in combiantion with EGFR-TKIs in tumor cells to guide rational use of combination therapies in clinical practice." (PMID 30953548, 2019). "Nectins and DeltaNp63 signaling pathways are known to be implicated in the tumor progression and anticancer drug resistance, but their potential roles in EGFR inhibitors resistance have not yet been studied." (PMID 30621238, 2019). "The epidermal growth factor receptor (EGFR) is a major regulator of proliferation in tumor cells." (PMID 31438847, 2019). "We also performed multi-regions ARMS EGFR detection in tissue section of each tumor sample." (PMID 31555581, 2019). "Similarly, BCL-XL and epidermal growth factor receptor (EGFR), both tumor suppressors, are also targeted by has-miR-608." (PMID 31450613, 2019). "Follow-up studies should analyse how other tumor cell lines act following 213Bi-anti-EGFR-MAb treatment with regard to [18F]FDG-uptake and pyruvate conversion as well as in vivo studies as this data only represents in vitro observations and can only transferred to in vivo situations with precaution." (PMID 31165773, 2019).
tumor (continued). "The percentage of cells containing MET pathway activation prior to EGFR-TKI treatment may determine whether the tumor cells present as intrinsic resistance or acquired resistance." (PMID 31815659, 2019). "In this study, the tracer was not able to distinguish tumours harbouring the T790 M resistance mutation from the other EGFR-mutated cells, but its presence is rare in TKI-naïve patients." (PMID 30612556, 2019). "In the HCC context, EGFR activity may repress the anti-tumor function of sorafenib, suggesting that the neutralization of EGFR may improve tumor response." (PMID 31370258, 2019). "We here used the CAM assay to analyze in vivo distribution of the nanoparticles and could identify EGFR-FITC-SiO2-NPs in the tumor and in the liver." (PMID 31561451, 2019). "This shows that inhibition or loss of EGFR induces CXCR7 expression in A549 cells and may subsequently contribute to tumor survival." (PMID 30935067, 2019). "Here, the authors show that activation of EGFR induces phosphorylation of this enzyme at Y481 to activate the pentose phosphate pathway, which consequently reduces ROS and accelerates DNA synthesis to promote tumor growth and radioresistance." (PMID 30824700, 2019). "Therefore, the activin A-mediated noncanonical pathway should be crucial for activation of the EGFR promoter since negative regulator canonical Smads were decreased in tumor tissues." (PMID 30914776, 2019). "In fact, ADCC induced by EGFR-specific mAbs may inhibit tumor progression in vivo, even in cancers resistant to EGFR signaling inhibition." (PMID 31500586, 2019). "The discordance in EGFR status may represent the heterogeneity of tumor clones, which could reflect different treatment responses in different individual patients." (PMID 31216329, 2019). "Alternatively, EMT might be induced very rapidly in some tumor cells after initiation of TKI-treatment as a form of adaptive response to the inhibition of EGFR signaling." (PMID 31266248, 2019). "In summary, our results suggest that the antitumor effects of xanthohumol could be mediated in part by the suppression of glycolysis through direct inhibitory effects on EGFR-Akt signaling and also via induction of apoptosis in tumor cells." (PMID 31595166, 2019). "Since recent observations show that targeting the EGFR signaling pathway can also trigger immunogenic cell death 12 or influence the tumor immune environment via the JAK/STAT3 axis, possible effects for immunotherapy or combination therapy are also of great interest." (PMID 30892828, 2019). "The interaction of HA and CD44 was found to promote epidermal growth factor receptor (EGFR)-mediated pathways in different tumor entities, in turn leading to tumor cell proliferation and survival via mitogen-activated protein kinase (MAPK) and phosphoinositide 3-kinase (PI3K)/AKT activation." (PMID 31052565, 2019). "While factors such as EGFR (epidermal growth factor receptor) mutation predict response to targeted therapy, tumor-specific prognostic factors are lacking." (PMID 30173391, 2019). "Studies also found adaptive reactivation of signal transducer and activator of transcription 3 (STAT3) within the minimal residual surviving drug persister tumor cells, which was co-activated with the SRC-YES-associated protein 1 (YAP1) pathway in EGFR-mutant NSCLC." (PMID 31815659, 2019). "It has been proposed that while these EGFR mutations occur after cetuximab therapy, they do not emerge after panitumumab therapy, leaving these tumor cells sensitive to panitumumab therapy." (PMID 31350822, 2019).
tumor (continued). "Interestingly, tons of studies have found that autophagy plays a part in the EGFR-TKI resistance of tumor cells." (PMID 31811814, 2019). "However, a multivariate analysis with tumor EGFR expression in combination with smoking above 10- and 20-pack years showed non-significant results for the smoking variable (p = 0.1 and p = 0.2)." (PMID 30630536, 2019). "uPAR is generally connected with tumor dormancy, EGFR is activated by uPAR (ligand-independent mode), sustaining cell proliferation via a mechanism where fibronectin/αvβI integrin and ERK are stimulated, finally leading to an increased metastatic rate in RAS-mutated tumors." (PMID 31652660, 2019). "To test whether the suppressive, ameliorative effects might be additive, we expressed NrgRNAi and diaRNAi simultaneously in EGFR-Pcn tumor cells." (PMID 31568500, 2019). "The most likely impact from this discovery will be in the identification of additional tumor patients that may benefit from EGFR TKI therapy." (PMID 31332182, 2019). "The NHIRD provides limited information on tumour stage or the EGFR status of patients." (PMID 31892709, 2019). "EGFR is known to affect growth and survival signals and to play a crucial role in the regulation of cell proliferation, differentiation, and migration of various tumor entities." (PMID 31438847, 2019). "Additionally, the increase in ctDNA EGFR copy number is consistent with the growth of MET inhibitor resistant tumor cells." (PMID 30849971, 2019). "EGFR therefore represents a bona fide drug target in triple-negative tumours." (PMID 31262335, 2019). "miR-27a was identified as a tumor suppressor in CRC, and it may directly target KRAS or EGFR to inhibit tumor cell growth." (PMID 31717759, 2019). "Thus, the interconnectivity between Pyk2 and EGFR signaling pathway, which regulates tumor development and metastasis, needs to be elucidated." (PMID 31368612, 2019). "Tumor tissues isolated from mice also showed that CuB inhibited EGFR and CIP2A expression in vivo." (PMID 30759826, 2019). "In addition, owing to the frequent aberrant expression levels of integrin β1 and EGFR in human cancer, previous studies have indicated that the integrin β1-EGFR signal pathway is the targeted option that can efficiently reduce tumor radioresistance." (PMID 31434965, 2019). "The detection of CTCs can reflect real-time tumor progression in patients, and the detection of molecular markers in CTCs can provide an important basis for the selection of therapeutic methods, especially EGFR detection in CTC." (PMID 31348821, 2019). "Therefore, EGFR-FITC-SiO2-NPs preferably bind to tumor tissue, and the malignant area can be visualized by confocal laser endomicroscopy." (PMID 31561451, 2019). "EGFR-TKIs have been found to induce anti-tumour effects via the inhibition of CIP2A." (PMID 31623614, 2019). "For three donors, EGFR levels on both normal and tumor organoids were compared." (PMID 31694307, 2019). "In total, 66 blood samples from NSCLC patients met the quality criteria regarding lack of haemolysis, known EGFR mutation in tumour tissue and paired cfDNA." (PMID 30953094, 2019). "We induced the EGFR-Pcn tumor model (with ap-Gal4, an epithelial cell-specific driver) together with CD8:GFP, a membrane-tethered GFP protein, and independently expressed membrane-tethered mCherry in the myoblasts (with 1151-lexA, lexO-mCherry-CAAX; a myoblast-specific driver)." (PMID 31568500, 2019). "The rise in epidermal growth factor receptor (EGFR; human epidermal growth factor receptor 1; HER1) expression and enhanced phosphorylation of HER2 and HER3 are associated with tumor resistance, metastasis and invasion, thus resulting in poor outcome of anti-CRC therapy." (PMID 31426807, 2019). "Furthermore, since Met overexpression and MET amplification has been implicated in acquired resistance to EGFR inhibition, we examined Met expression in MGG70R and MGG70RR patient tumour specimens and the respective GSC tumours." (PMID 30644426, 2019).
tumor (continued). "Despite that a handful of reports has suggested that radiation sensitivity of tumor cells is negatively correlated to the expression levels of EGFR and VEGF, our study, nevertheless, firstly report that oral administration of TNuF effectively suppresses EGFR upon radiation." (PMID 31426614, 2019). "In the nucleus, EGFR is capable to activate pathways that are associated with tumor resistance to therapy-induced DNA damage and anti-EGFR treatment, in a mechanism that is independent of its conventional signaling from the plasma membrane." (PMID 31877735, 2019). "In this study, we investigated whether canine non-B, non-T NK cells possess ADCC function against antibody-coated tumor cells, using cetuximab and trastuzumab, the human antibodies reported to bind to canine cancer cells expressing EGFR and HER-2." (PMID 31610784, 2019). "Also, Anti-EGFR leads to 0.77±0.128 and 0.86±0.157 fold tumor growth at 3 and 5 weeks after castration relative to castration only, which are close to the experimental observation of in vivo effects of EGFR inhibitors in 22RV1 xenografts mice model." (PMID 31504033, 2019). "A similar approach was used to investigate the regulation and role of EGFR in luminal BC where the knockdown of TFAP2C has induced decreased expression of EGFR in a panel of this tumor and, consistently, the EGFR gene has resulted by ChIP-seq to be a TFAP2C target." (PMID 35582269, 2019). "EGFR and c-Met are known to trigger similar signal transduction pathways and their crosstalk in solid tumors affects the duration and strength of the response and overall tumor malignancy." (PMID 31467533, 2019). "To determine whether this is also the case in tumor tissues, we compared the protein levels of TF and EGFR in human 144 HCC tissues by IHC assay." (PMID 30931258, 2019). "Plasma concentrations of AXL and GAS6 do not reflect tumor expression levels, and their measurement is thus not a viable alternative to direct analysis of tumor tissue in EGFR‐mutated NSCLC." (PMID 31419057, 2019). "EGF has been reported to induce focal adhesion disassembly and enhance tumour cell motility through EGFR-activated E-cadherin endocytosis, and SGSM2 has been reported to interact with RAB family proteins, who function in recycling of vacuoles between the early endosome and plasma membrane." (PMID 30744493, 2019). "Likewise, co-administration of GANT61 with erlotinib (an EGFR inhibitor) has been reported to impair tumor initiating properties of pancreatic cancer cells, and to reduce tumor growth in HH-driven BCC mouse models." (PMID 31244888, 2019). "Although our results are confined to the intratumor injection model, our study shows that the affibody probes could specifically target EGFR-expressing tumor cells and induce tumor cell damage." (PMID 30669481, 2019). "Rechallenge with TKI in NSCLC patients with EGFR mutations relies on the hypothesis that only a fraction of the EGFR-mutant tumor cells acquires a second genetic alteration that determines resistance." (PMID 31557965, 2019). "In our study, two patients had different EGFR genotypes shown in tumor tissue and ctDNA, which might be related to molecular heterogeneity." (PMID 31652678, 2019). "Additionally, targeting IL-6 in combination with EGFR inhibitors such as Cituximab is currently being investigated as a potential therapy for HNSCC due to the resistance to EGFR inhibition seen in many tumours." (PMID 31226168, 2019). "In addition, the first in vivo assays showed promising results of our EGFR degraders in inhibiting the tumor growth in mice." (PMID 31374910, 2019). "Treatment failure with EGFR inhibitors in HCC patients may cause by many reasons, such as the levels and mutations of EGFR, EMT status of tumor cells, etc.." (PMID 30931258, 2019).